IL10 (interleukin 10)
Diseases named in the same sentence as IL10 in open-access papers (continued):
Sharing a sentence is not in itself a finding about the gene and the disease.
ischemic stroke (continued). "Our findings suggest three genes (PDE4D, ACE I/D and IL10) to have statistically significant ORs for risk of ischemic stroke in a South Asian adult population and the totality of data supported MTHFR C677T as a further likely risk factor." (PMID 23505425, 2013). "Further studies are warranted to confirm whether the protective association of IL-10 with prognosis represents a causal pathway involved in the pathogenesis or the predictive effect of poor prognosis on ischemic stroke patients." (PMID 34336007, 2021). "A failure in this system could promote worse neurological outcomes since lower IL-10 plasma levels were associated with clinical worsening in ischemic stroke patients." (PMID 32719588, 2020). "Therefore, the significance of IL-10 for assessment of ischemic stroke outcome and risk is ambiguous." (PMID 31701356, 2020). "Interestingly this is supported by a clinical study, demonstrating that lower IL-10 plasma concentrations in acute ischaemic stroke patients is associated with clinical worsening." (PMID 31572381, 2019). "Summary of clinical ischemic stroke studies investigating IL-10 genetic polymorphisms." (PMID 28659854, 2017). "There is evidence that interleukin-10 (IL-10) associates with ischemic stroke." (PMID 25923658, 2015). "We assessed whether serum interleukin-10 (IL-10) and its genetic variations are associated with ischemic stroke in a Chinese general population." (PMID 24040186, 2013). "Despite these limitations, our study provides new evidence that lower serum IL-10 and its genetic variations (AA genotype of rs1800872, TT genotype of rs1554286, and CA/CC genotype of rs3021094) are associated with an increased likelihood of ischemic stroke." (PMID 24040186, 2013). "Thus, IL-10 and its three SNPs have a potentially important role in clinical practice for the estimation of an individual’s predisposition to ischemic stroke." (PMID 24040186, 2013). "IL-10 SNPs and risk of ischemic stroke in 1475 participants." (PMID 24040186, 2013). "We also examined whether these SNPs together with IL-10 improved the risk prediction of ischemic stroke above that of classical risk factors in this population." (PMID 24040186, 2013). "Thus, in the current study we selected rs1800872, rs1554286 and rs3021094 SNPs and examined the relationships between serum IL-10, selected IL-10 gene SNPs, and the risk of ischemic stroke using a cross-sectional study in a general Chinese population." (PMID 24040186, 2013). "Exclusion of high risk participants however is only likely to attenuate the strength of the associations observed because the association between IL-10 and SNPs and ischemic stroke is stronger in high-risk participants than in low-risk participants in the present study (data were not shown)." (PMID 24040186, 2013). "Our results show that a higher serum IL-10 level may be associated with a reduced risk of ischemic stroke in a general population." (PMID 24040186, 2013). "Additionally, in a study about the relationship between ex vivo cytokine synthesis and 3-month outcomes after ischemic stroke, decreased release of IP-10, TNFα, IL-1β, and IL-12; increased release of IL-10 and IL-8; and higher plasma IL-6 levels were associated with poor outcomes." (PMID 36439158, 2022). "The low baseline levels and loss of early upregulation of IL-10 in spontaneously hypertensive rats (SHRs) 24 h after MCAO shows an impaired anti-inflammatory response after ischemic stroke that might be associated with the impaired recovery and worsened outcome in these animals." (PMID 24499655, 2013). "Even cytokines considered beneficial, such as IL-6 and IL-10, which promote angiogenesis and functional recovery, are potential therapeutic targets for ischemic stroke." (PMID 40364646, 2026). "Conversely, the levels of the anti-inflammatory IL-10 were found to be reduced in the initial phase of ischemic stroke, leading to a worse clinical outcome." (PMID 40364646, 2026).
ischemic stroke (continued). "Elevations in proinflammatory cytokines and reductions in anti-inflammatory IL-10 correlate with larger infarction volumes and worse clinical outcomes following ischemic stroke." (PMID 40095189, 2025). "Treg cells primarily prevented secondary brain injury by coordinating lymphocyte and microglia infiltration in ischemic stroke through IL-10 signaling." (PMID 40134421, 2025). "This work follows recently published data from our group that also showed therapeutic efficacy of IL-10 mRNA in an experimental model of ischemic stroke using a different formulation of commercially available LNPs targeted to VCAM27." (PMID 40297702, 2025). "Comparing the prognosis of ischemic stroke patients between survivors and non survivors, the IL-10 level in the survivors group was significantly higher than that in the non survivors group (P=0.006)." (PMID 40134421, 2025). "Experimental studies have shown that IL-10 overexpression or exogenous administration reduces infarct volumes and improves neurological outcomes in animal models of ischemic stroke." (PMID 40869247, 2025). "Interleukins such as TNF-α, IL-2, IL-4, IL-6 and IL-10, secreted by lymphocytes, play an important role in the pathogenesis and prognosis of ischemic stroke." (PMID 39204113, 2024). "For example, the injection of 1 μg of IL-10 resulted in a reduction in infarct size in an ischemic stroke model in rats." (PMID 40066118, 2024). "Nevertheless, when compared to the ischemic stroke, only several studies analyzed IL‐6 and IL‐10 in the ICH setting, and only a few showed correlations with neuroimaging variables." (PMID 35762501, 2023). "Ischemic stroke is protected against thanks to IL-10 treatment’s ability to effectively down-regulate the upregulated proinflammatory signals in acute ischemic lesions." (PMID 36793730, 2023). "Intraventricular MCS transplantation, performed 1 day post ischemic stroke, reportedly upregulated IL-10 and reduced tumor necrosis factor (TNF)-alpha 4 days post ischemic stroke." (PMID 36671605, 2022). "Treg also produces IL-10 and contributes to reduction of the infarct volume 7 days post ischemic stroke." (PMID 36671605, 2022). "Upregulation of these important proinflammatory mediators in Il10-KO CD8+ TRL–treated mice suggests that IL-10 signaling mediates the antiinflammatory properties of CD8+ TRLs after ischemic stroke." (PMID 35912857, 2022). "The controversy in the role of IL-10 in ischemic stroke and fewer studies in females illustrate the necessities of more targeted studies to evaluate precise contribution of IL-10 following acute brain injuries." (PMID 35413803, 2022). "In transgenic mice that overexpressed IL-10, infarct size was reduced, and apoptosis was limited 4 days post ischemic stroke." (PMID 35173738, 2022). "The levels of IL-1, TNF-alfa, IL-23, and IL-17 in the blood were reduced, and the level of IL-10 was increased until 1 week post ischemic stroke." (PMID 36671605, 2022). "By contrast, a significant decrease in IL-10 gene expression was found 24 and 48 h after an ischemic stroke compared to CT subjects." (PMID 34201498, 2021). "The polarization of M2 microglia commenced several days after ischemic stroke and was induced by IL-4, IL-10, vascular endothelial-derived growth factor (VEGF), and GSF secreted from neurons." (PMID 34248961, 2021). "Additional large sample and multicenter studies assessing the role of IL-10 in ischemic stroke are warranted." (PMID 34336007, 2021). "We showed that salivary TNF-α and IL-6 were significantly higher, whereas IL-10 content was statistically lower in ischemic stroke patients than healthy controls." (PMID 34433866, 2021). "IL-10 reduces infarct volumes in murine ischaemic stroke, and IL-10-secreting B cells have been found in HIE, suggesting B cells as essential protectors of the brain after HI." (PMID 34755125, 2021).
ischemic stroke (continued). "Reduced serum levels of IL-10 were independently associated with both the clinical severity at admission and a poor functional prognosis in ischemic stroke patients, suggesting that the anti-inflammatory cytokine IL-10 was an important prognostic determinant." (PMID 34336007, 2021). "These novel investigations that report upregulation of systemic IL-10 after SAH are consistent with the results of earlier investigations of ischemic stroke, intracerebral hemorrhage or traumatic brain injury." (PMID 32106601, 2020). "The increased IL-10 serum levels have been revealed in patients with severe neurological impairment assessed by NIHSS score at 48 h after the ischemic stroke onset." (PMID 31701356, 2020). "A follow-up study demonstrated that adoptive transfer of IL-10-producing MOG-specific CD4+ T cells conferred neuroprotection after ischemic stroke." (PMID 31572381, 2019). "After the ischemic stroke, it can reduce the infarct volume by 40% in the IL-10 transgenic mice when compared with that of the wild type mice." (PMID 31801113, 2019). "Studies have found that the expression levels of IL-4, IL-5, IL-6, and IL-10 are increased remarkably in the damaged hemisphere after ischemic stroke." (PMID 31164999, 2019). "After ischemic stroke, it can reduce the infarct volume by 40% in the IL-10 transgenic mice with overexpressed IL-10 in astrocytes, microglia, and endothelial brain cells when compared with that of the wild type mice." (PMID 27456198, 2016). "High levels of serum IL-10 have been suggested to facilitate the selection of ischemic stroke patients with salvageable brain tissue for systemic thrombolysis." (PMID 25923658, 2015). "High serum concentration of IL-10 predicts the presence of salvageable ischemic tissue after ischemic stroke." (PMID 25923658, 2015). "Our results suggest that activated Tregs promoted NSC proliferation via IL-10, which provides a new therapeutic approach for ischemic stroke." (PMID 26441532, 2015). "The distribution of age-sex-adjusted tertiles of IL-10 was significantly different between patients with ischemic stroke and controls (p=0.013)." (PMID 24040186, 2013). "While a recent study has underscored the functional protective role of IL-10 in ischemic stroke through ameliorating brain inflammation, further investigations are needed to examine the mechanisms involved in IL-10 upregulation post-ischemia." (PMID 24499655, 2013). "In this investigation we aimed at determining the temporospatial expression of IL-10 in the rat brain relative to its systemic levels after ischemic stroke." (PMID 24499655, 2013). "The SNP score (a summary index of these SNPs) and IL-10 (top tertile) together significantly improved the discriminative power in predicting ischemic stroke by 3.3% (95%CI: 0.2-6.4, p=0.0398) compared to predictions based on conventional risk factors alone." (PMID 24040186, 2013). "In summary, our study highlights the contribution of the ischemic and contralesional neurons to the anti-inflammatory response after ischemic stroke through upregulation of IL-10." (PMID 24499655, 2013). "Animal studies have confirmed the anticipated neuroprotective role of the anti-inflammatory cytokine, interleukin 10 (IL-10), in ischemic stroke." (PMID 24499655, 2013). "Serum levels of IL-10 facilitate the selection of ischemic stroke patients with CDM and PDM for systemic thrombolysis." (PMID 23773291, 2013). "Our data highlights the involvement of the ischemic and contralesional neurons in the endogenous anti-inflammatory response after ischemic stroke through increased production of IL-10." (PMID 24499655, 2013). "highlighted the central role of MMPs in regulating blood-brain barrier permeability in ischaemic stroke; In contrast, lymphocytes – particularly Treg cells – suppress excessive inflammation through anti-inflammatory cytokines such as IL-10 and TGF-β, facilitating tissue repair." (PMID 41527423, 2026).
ischemic stroke (continued). "Indeed, IL-10 plays a relevant role in ischemic stroke, suppressing pro-inflammatory signals and dampening immune responses." (PMID 40364646, 2026). "Previous studies have demonstrated that newly repopulated microglia had reduced expression of inflammatory markers (e.g., IL-1β, IL-6, TNF-α and CD86), and upregulation of neuroprotective factors (e.g., CD206, TGF-β, and IL-10) in response to ICH ischemic stroke in ageing." (PMID 40777042, 2025). "In addition to major cytokines like IL-1β, IL-6, TNF-α, and IL-10, several other inflammatory mediators play significant roles in ischemic stroke." (PMID 40869247, 2025). "Furthermore, individuals receiving edaravone dexborneol injection exhibited lower expression levels of interleukin (IL)-1β, IL-6, and IL-17, along with higher levels of IL-4 and IL-10 expression during the acute phase of ischemic stroke (P < 0.05)." (PMID 38902691, 2024). "Notably, interleukin-10 expression in optogenetic-activated astrocytes significantly increased after ischemic stroke in rats." (PMID 37196130, 2023). "Because microglial polarization to the M2 type promotes brain repair and confers a beneficial effect after ischemic stroke, we investigated whether 2′-FL regulates IL-10 and TNF-α secretion using ELISA." (PMID 37372011, 2023). "It was reported that IL-10 had generally no significant relation with the risk of ischaemic stroke, but was associated with macro-vascular and micro-vascular disease." (PMID 36600830, 2023). "In one experiment of ischemic stroke, IL-10 was present in both hemispheres of the brain." (PMID 38131062, 2023). "MSCs could release anti-inflammatory (such as interleukin-10 [IL-10], IL-13), pro-inflammatory (such as IL-8, IL-1α, IL-12), and pleiotropic cytokines (IL-6, IL-11, IL-16, IL-1β) to regulate immune function after ischemic stroke." (PMID 35551643, 2022). "In contrast, interleukin-10 (IL-10) is a key anti-inflammatory cytokine following ischemic stroke." (PMID 36203971, 2022). "Either administration of stem cells themselves or hematopoietic cytokines may ameliorate ischemic stroke injury partially through the increase of IL-10." (PMID 35173738, 2022). "In vitro and in vivo models of ischemic stroke showed the neuroprotection of IL-10." (PMID 36203971, 2022). "The neuroprotection of IL-10 on ischemic stroke has always been a research hotspot." (PMID 35173738, 2022). "These facts indicate a complicated network between IL-10 and immune cells in ischemic stroke." (PMID 35173738, 2022). "Hematopoietic cytokines such as GCSF and stem cell factor have been confirmed to promote neurogenesis, and also may be required to provide the initial signals for IL-10 production in ischemic stroke." (PMID 35173738, 2022). "Administration of hematopoietic cytokines could increase the expression of IL-10, which might provide a favorable microenvironment for neurogenesis after ischemic stroke." (PMID 34336007, 2021). "In patients with ischemic stroke, the role of anti-inflammatory cytokine Interleukin-10 (IL-10) in predicting risk and outcomes is not very clear." (PMID 34336007, 2021). "Our previous study showed that GSS increased IL-10 expression in peri-infarcted regions in ischemic stroke rats (unpublished data), implying that GSS might promote microglia depolarization to M2 phenotype, which requires future research." (PMID 33867831, 2021). "B-cells can also contribute to neuroprotection after the ischemic stroke, depending on IL-10." (PMID 34502395, 2021). "In patients with ischemic stroke, the role of IL-10 in predicting risk and outcomes is not very clear." (PMID 34336007, 2021). "The IL-10 expression increases in acute phase of ischemic stroke." (PMID 31701356, 2020). "The results showed higher levels of IL-10 in patients with ischemic stroke compared with controls." (PMID 32111174, 2020).
ischemic stroke (continued). "Treg were also correlated with IL-10 levels, supporting that this anti-inflammatory cytokine may play an important role in the beneficial effects of these cells after ischemic stroke." (PMID 32111174, 2020). "Considering the significant correlation of anti-inflammatory cytokine IL-10 and neurological function in our study, we suggested modulation of neuroinflammatory responses shed promising light on neurological recovery following ischemic stroke." (PMID 31810470, 2019). "However, the powerful relationship between IL‐10 (−1082A/G) and ischemic stroke has been found in the Italian population." (PMID 31571432, 2019). "In this study, we found that higher levels of IL-10 were associated with poor acute and long-term outcomes after ischemic stroke in female patients but not in males." (PMID 26462256, 2015). "In addition, the number of peripheral blood mononuclear cells (PBMC) secreting IL-10 has been shown to be elevated in patients with ischemic stroke and cerebral hemorrhage." (PMID 25923658, 2015). "As an anti-inflammatory cytokine, IL-10 can suppress the inflammatory cascade following ischemic brain injury, which has been confirmed in the animal model of ischemic stroke using exogenous IL-10, IL-10-overexpressing transgenic mice and IL-10-expressing virus-vector." (PMID 26366999, 2015). "Relationship between interleukin-10 (IL-10) and ischemic stroke in 1475 participants." (PMID 24040186, 2013). "However, IL-10 is increased in the serum and CSF of patients after ischemic stroke with conflicting reports on its correlation with improved versus worsened outcome." (PMID 24499655, 2013). "Therefore, we further assessed the additional value of serum IL-10 and SNPs in predicting ischemic stroke over and above that of a prognostic model with conventional risk factors alone." (PMID 24040186, 2013). "Thus, the role of B-cells in ischemic stroke is contradictory, and the positive effects of IL-10 on the local inflammatory milieu may be counterbalanced by the negative effects of its autocrine antibodies." (PMID 38550918, 2024). "Importantly, after an ischemic stroke, IL-10-producing regulatory B cells play a protective effect." (PMID 36793730, 2023). "Similarly, regulatory B lymphocytes may also play a protective role in ischemic stroke by regulating anti-inflammatory factors such as IL-10 and transforming growth factor (TGF)-β." (PMID 35656406, 2022). "It is unknown whether sex differences exist in the IL-10 response after ischemic stroke." (PMID 26462256, 2015). "The aim of this prospective study was to assess the levels of IL-10 in ischemic stroke with unknown or suspected cardiogenic etiology, and evaluate the correlation between IL-10 plasma concentration and the number of diagnosed high risk sources for cardioembolism." (PMID 25923658, 2015). "Cytokines play a pivotal role in the inflammatory response following an ischemic stroke with TNF-α, IL-1β, IL-6, and IL-10 being particularly significant." (PMID 40095189, 2025). "In ischemic stroke, microglia polarize into distinct phenotypes: pro-inflammatory M1 (secreting TNF-α, IL-1β, IL-6) and pro-angiogenic M2 (releasing IL-10, TGF-β, VEGF)." (PMID 40988927, 2025). "Additionally, inflammation-regulating proteins like transforming growth factor-beta (TGF-β) and interleukin-10 (IL-10) are employed to reduce nerve damage and facilitate nerve repair, aiming to suppress the inflammatory response and improve recovery outcomes in patients with ischemic stroke." (PMID 39126107, 2024). "Accumulating evidence indicates that combination therapy of MSCs and IL10 protein could have synergistic effects to reduce inflammation in various diseases such as experimental autoimmune encephalomyelitis, ischemia–reperfusion injury in the lung, and ischemic stroke." (PMID 35300585, 2022). "Microglia directly protect the BBB from damage through secretion of IL-10 and TGF-β in ischemic stroke." (PMID 34248961, 2021).